RNU6-1079P (RNA, U6 small nuclear 1079, pseudogene)
Gene: Small nuclear RNA gene on chromosome 5 (32,234,766 to 32,234,875, reverse strand). Ensembl gene ENSG00000199731.
Homologues: Orthologues: chimpanzee U6 (100% identical), macaque U6 (88% identical), rabbit U6 (84% identical), pig U6 (77% identical), mouse Gm23242 (69% identical). Paralogues in human: RNU6-35P (85% identical), RNU6-1155P (85% identical), RNU6-1316P (85% identical), RNU6-188P (85% identical), RNU6-25P (85% identical), RNU6-38P (85% identical), RNU6-820P (85% identical), RNU6-1 (84% identical), RNU6-1158P (84% identical), RNU6-11P (84% identical), RNU6-15P (84% identical), RNU6-19P (84% identical), and 1286 more.